ARR3 (arrestin 3)
Diseases named in the same sentence as ARR3 in open-access papers (continued):
Sharing a sentence is not in itself a finding about the gene and the disease.
respiratory depression (2 papers, 2021 to 2024). A decrease in ventilation secondary to impaired signals from the central nervous system. "The prevailing hypothesis is that the intended analgesic effects of opioid drugs are mediated by μ-opioid receptor signaling to G protein, while the side-effects of respiratory depression and analgesic tolerance are caused by engagement of the receptor with the arrestin-3 protein." (PMID 34257415, 2021). "Previous studies report that loss of arrestin-3 engagement, either using Arr-3 KO mice or novel, putative G-biased MOR agonists, reduces opioid-induced respiratory depression although that has been recently challenged." (PMID 34257415, 2021). "We assessed respiratory depression with whole-body plethysmography in WT, Arr-3 KO and RMOR mice in response to the AD80 dose of morphine for each genotype." (PMID 34257415, 2021). "To clarify the role of arrestin-3 in the opioid side-effects of respiratory depression and tolerance, we examined six clinically relevant opioids with varying G protein biases at equi-analgesic doses." (PMID 34257415, 2021). "This push to develop ultra-G-biased ligands followed reports that Arr3-KO mice show increased analgesia and reduced tolerance and respiratory depression in response to morphine compared to WT mice, indicating that biased ligands could ameliorate these key side effects." (PMID 39391692, 2024). "This implied that enhanced arrestin-3 recruitment, as occurs in RMOR mice, should increase respiratory depression." (PMID 34257415, 2021). "Mice without the arrestin-3 gene (Arr3-KO) were reported to show increased analgesia, reduced tolerance, and reduced respiratory depression and constipation in response to morphine compared to wild type (WT) mice." (PMID 39391692, 2024). "Another genetically modified mouse, which lacks phosphorylation of MOR (a phospho-null mouse) and consequently, arrestin-3 recruitment, also does not show improved respiratory depression." (PMID 34257415, 2021). "While arrestin-3 recruitment at MOR appears unrelated to respiratory depression, we found a strong negative correlation between the development of analgesic tolerance in vivo and arrestin-3 recruitment in vitro using a diverse panel of opioids." (PMID 34257415, 2021). "All of this implicates G protein activity over arrestin-3 as the key player in opioid-induced respiratory depression, leaving no clear way to separate the analgesic and respiratory mechanisms of these drugs." (PMID 34257415, 2021). "Here, we examine respiratory side-effects in these mice and show that arrestin-3 engagement at MOR does not exacerbate respiratory depression and protects against the development of analgesic tolerance." (PMID 34257415, 2021). "RMOR and WT mice showed comparable respiratory depression in response to equi-analgesic morphine, indicating arrestin-3 engagement does not exacerbate respiratory depression." (PMID 34257415, 2021). "With this genetic and pharmacological approach, we demonstrate that arrestin-3 recruitment does not impact respiratory depression, and effective arrestin-3 engagement reduces, rather than exacerbates, the development of analgesic tolerance." (PMID 34257415, 2021). "However, several recent reports have failed to reproduce these findings in Arr3-KO mice and clinically, Oliceridine did not significantly reduce respiratory depression." (PMID 39391692, 2024). "To circumvent the variable of intrinsic efficacy (as well as different pharmacokinetics or other ligand properties), we used RMOR mice to show that tolerance to morphine is reduced by enhancing arrestin-3 engagement by the receptor without any increase in the respiratory depression." (PMID 34257415, 2021). "However, mice with a chimeric MOR that is an improved substrate for GRKs and have enhanced arrestin-3 recruitment (RMOR mice, for recycling MOR) also show enhanced analgesia and reduced analgesic tolerance to morphine with no change in respiratory depression." (PMID 39391692, 2024).
depression (1 paper, 2021). "In contrast to the original report, Arr-3 KO also showed equivalent respiratory depression compared to WTs, supporting recent reports from three independent laboratories." (PMID 34257415, 2021).
dysautonomia (1 paper, 2025). An acute or chronic disorder, affecting the sympathetic or parasympathetic nervous system. "Therefore, a decreased efficacy of ACh in stimulating Gi protein signal transduction, combined with Arr-3-mediated M2R desensitization and internalization, would result in a reduction in ACh-induced negative chronotropic response, leading to parasympathetic dysautonomia." (PMID 41369345, 2025).
Impaired glucose tolerance (1 paper, 2014). An abnormal resistance to glucose, i.e., a reduction in the ability to maintain glucose levels in the blood stream within normal limits following oral or intravenous administration of glucose. "Arr3-knockout mice displayed impaired glucose tolerance and insulin secretion; however, GLP-1 amplification of insulin secretion was not affected." (PMID 25191754, 2014).
Parkinson disease (1 paper, 2024). A progressive degenerative disorder of the central nervous system characterized by loss of dopamine producing neurons in the substantia nigra and the presence of Lewy bodies in the substantia nigra and locus coeruleus. "Moreover, arrestin-3 was shown to rescue the activity of enzymatically impaired disease-causing parkin mutant R275W, suggesting that arrestin-3-based molecular tools might prevent the root cause of Parkinson’s disease, namely the demise of dopaminergic neurons in substantia nigra." (PMID 38892473, 2024).
type 2 diabetes (1 paper, 2023). "Direct investigation of 40 type 2 diabetes-associated variants of the MT2 receptor revealed that mutations determining a bias towards arrestin 3 recruitment, rather than Gαi/o, have the most statistically significant associations with increased type 2 diabetes risk." (PMID 37371671, 2023).
vision disorder (1 paper, 2022). Any impairment to the vision. "Based on this article it was decided to perform an additional analysis of the ARR3 gene on the X‐chromosome because this gene was not in the panel for vision disorders and the paternal inherited mutation on the X chromosome had not been prioritized, due to the rare inheritance pattern." (PMID 35001458, 2022).
X-linked recessive disease (1 paper, 2023). X-linked recessive form of disease. "Because the Arr3 gene is located on X-chromosome, we observed mosaicism in SW-AF images acquired from Arr3P2ACreERT2/+Ai14D+/- mice, which in SW-AF images phenocopies the mosaic retinopathy in carriers of hereditary X-linked recessive diseases." (PMID 37381060, 2023).
tumor (8 papers, 2018 to 2024). "The CRX+/ARR3+/GUCA1C+ tumor population (clusters 1 and 4) was less unstable and consisted of two genomically different subpopulations." (PMID 34552068, 2021). "Cells from clusters 1 and 4 (CRX+/ARR3+/GUCA1C+ tumor cells) corresponded to the last two profiles (10q gain ± 2p gain)." (PMID 34552068, 2021). "Both small and large patient-derived tumorspheres, as well as Y79 cells, were positive stained for arrestin 3 and synaptophysin, confirming the retinal and neuroectodermic tumor cell origin." (PMID 30832308, 2019). "In contrast, the expression levels of cone-enriched genes (PDE6C and ARR3) were high in tumor and further enriched in organoids, compared with fetal retina." (PMID 30353124, 2018). "Immunohistochemical analysis of this tumor showed a mutually exclusive expression of ARR3 and EBF3, defining two types of areas (CRX+/ARR3+/EBF3− and CRX+/ARR3−/EBF3+), as observed in about 30% of subtype 2 tumors." (PMID 34552068, 2021). "We then examined the expression of retinal-associated genes within a set of differentially expressed genes following MYCNOS1 silencing and found that expression of cone genes, including ARR3, GNAT, and PDE6C, was downregulated in MYCNOS1-depleted tumor cells." (PMID 33270844, 2020). "Among the identified RB tumor marker genes are known RB markers like the immature precursor gene CRX as well as genes of mature photoreceptors including phosphodiesterase 6H (PDE6AH) and arrestin 3 (ARR3), specific for cones." (PMID 39695086, 2024). "RB170 tumor cells had cone properties, as shown by CRX and ARR3 expression." (PMID 33270844, 2020).
ARR3 also shares sentences with these, for which no sentence is quoted: myopic maculopathy (3 papers); cancer (2); glaucoma (2); Photophobia (2); retinal degeneration (2); retinopathy (2); achromatopsia (1); Astigmatism (1); cataract (1); dependence (1); infection (1); lung carcinoma (1); neurodevelopmental disorder (1); retinal detachment (1).